BTG2 (BTG anti-proliferation factor 2)
Diseases named in the same sentence as BTG2 in open-access papers (continued):
Sharing a sentence is not in itself a finding about the gene and the disease.
cancer (continued). "The APRO family includes 6 members: Tob1, Tob2, BTG1, BTG2, Abundant in Neuroepithelium Area (ANA), and BTG4, which some members are of significance for the prognosis of cancers." (PMID 40918450, 2025). "In these ways, APRO family proteins including Tob1, BTG2, and BTG1 have been reported to control/regulate/promote cell proliferation, cell cycle progression, and/or cell differentiation in various types of cancer." (PMID 40918450, 2025). "Through a series of bioinformatics analysis, the findings in our study supported the important role of TOB1, TOB2, BTG1, BTG2, BTG3 and BTG4 in pan-cancer and provided a reliable basis for detecting biomarkers of cancer." (PMID 38062199, 2023). "Ectopic overexpression of Btg2 inhibited the EMT response, blocking cell migration, and promoted cancer cell death." (PMID 36765032, 2023). "In the present study, we comprehensively analyzed the role of TOB1, TOB2, BTG1, BTG2, BTG3 and BTG4 in cancer from the perspective of bioinformatics." (PMID 38062199, 2023). "We used bioinformatics methods to analyze the characteristics of TOB1, TOB2, BTG1, BTG2, BTG3 and BTG4 in pan-cancer." (PMID 38062199, 2023). "MiR-27a-3p upregulation has been identified in a variety of human cancers, and miR-27a-3p modulates cancer progression by targeting multiple targets including NOVA1, FBXW7 and BTG2." (PMID 35348441, 2022). "B-cell translocation gene 2 (BTG2), the first gene identified in the BTG/TOB gene family, is proved to be involved in many biological activities in cancer cells." (PMID 34861847, 2021). "Determination of the role of BTG2 in HCC progression and metastasis unveil its novel functions in the progression and metastasis of malignant cancers." (PMID 32746503, 2020). "By inhibiting B cell translocation gene 2 (BTG2), miR-27-3p can upregulate the Ras/MEK/ERK pathway and c-myc levels, promoting cancer cell proliferation." (PMID 31572683, 2019). "The miR-27 displays its oncogenic property through regulating the expression of target genes including FOXO1, BTG2, PHB and other cancer-related genes." (PMID 28415619, 2017). "Additionally, we investigated the impact of NOX2 on the biological functions of ESCC cells and its relationship with the BTG2 pathway to elucidate the connection between NOX2 expression and cancer progression." (PMID 41441930, 2025). "Survival analysis for BTG2 expression was performed in 97 cancer samples using the median method; the expression BTG2 did not impact the survival time of patients." (PMID 36841760, 2023). "Thus, according to MirAnalyze database, let-7a-5p, miRNA-16-5p, -21-5p share common target genes as follows: B-cell translocation gene 2 (BTG 2), and fibroblast growth factor receptor substrate 2 (FGFR2), which change their expression in cancer." (PMID 34434498, 2021). "Moreover, miR-21 anti-apoptotic effects are also achieved through its inhibition of B cell translocation gene 2 (BTG2), a gene involved in cell proliferation, DNA damage repair, differentiation, and apoptosis in cancer cells." (PMID 32192047, 2020). "Altogether, the transcriptional expression levels of TOB1-2 and BTG2 were significantly reduced in most cancers compared with normal tissues, while BTG3 was upregulated in most cancers." (PMID 28922388, 2017). "B-cell translocation gene 2 (BTG2), also known as PC3 (pheochromocytoma cell 3) or TIS21 (tetradecanoyl phorbol acetate-inducible sequence), belongs to the antiproliferative (APRO) gene family, and is involved in many biological activities in cancer cells." (PMID 26132560, 2015). "Targets of miR-21 in cancer include PTEN, PDCD4, LRRFIP1, RECK, TIMP-3, TPM1, BTG2, and Sprty2." (PMID 25366985, 2014).
cancer (continued). "BTG2 is differentially expressed between various cancers and normal tissues." (PMID 37006240, 2023). "However, despite its importance in several biological processes and in human cancers, the precise molecular function of BTG2 is not well defined." (PMID 26912148, 2016). "For modules M3, M4, and M5, although the corresponding GO_BP terms were not directly related to cancer, we found PrCa-relevant genes in these three modules, including BTG2, FOS (also known as c-Fos), and CXCR4 in module M3; ARFGAP3 and CDH1 in module M4; and SMAD3 and MXI1 in module M5." (PMID 25418933, 2014). "In B‐cell precursor acute lymphoblastic leukemia (BCP‐ALL), the most common type of cancer in children, microdeletions affecting BTG1, but not BTG2, are recurrently detected." (PMID 30350856, 2019). "BTG2 had been reported to inhibit Src-FAK (focal adhesion kinase) signaling by downregulating reactive oxygen species (ROS) generation and therefore exert a negative effect on cancer cell metastasis." (PMID 34861847, 2021). "Moreover, BTG2 over‐expression inhibits interleukin‐6 (IL‐6) expression through downregulation in the STAT3 pathway, as well as inhibiting reactive oxygen species (ROS) generation in the JAK2‐STAT3 signalling pathway; thus it has a negative effect on cancer cell growth." (PMID 29656435, 2018).
infection (9 papers, 2011 to 2023). The state of being infected such as from the introduction of a foreign agent such as serum, vaccine, antigenic substance or organism. "During primary infection, hub protein such as Elavl1, Btg2, Fkbp5, Hug, Hsp90a.1 are also top in the betweenness ranking." (PMID 25341656, 2014). "The p21 and Btg2 transcripts both increased >10-fold 8 h post-infection." (PMID 22114676, 2011). "Baseline BTG2 mRNA is undetectable in MDA-MB-231 cells, facilitating measurement of its induction 3 days after infection." (PMID 26394836, 2015).
immune disorder (3 papers, 2021 to 2023). "EGR1 expression trajectory in aged HSC highlighted a signature enriched in hematopoietic and immune disorders with the best induction of AP-1 complex and quiescence regulators such as EGR1, BTG2, JUNB, and NR41A." (PMID 34294125, 2021).
cardiovascular disease (2 papers, 2024 to 2025). "Its relationship with cardiovascular disease is multifaceted: BTG2 acts as a key regulator that suppresses excessive cardiomyocyte proliferation." (PMID 39749331, 2024).
colon (1 paper, 2023). "M6A reader YTHDF2-mediated degradation of ADAMTS9-AS2 promotes colon carcinogenesis via miR-27a-3p/BTG2 axis." (PMID 36816363, 2023).
BTG2 also shares sentences with these, for which no sentence is quoted: glioblastoma (3 papers); diffuse large B-cell lymphoma (2); insomnia (2); metastatic disease (2); multiple myeloma (2); nasopharyngeal carcinoma (2); neurodegenerative disease (2); osteoarthritis (2); acute lymphoid leukemia (1); acute myeloid leukaemia (1); adenoma (1); alcoholic liver diseases (1); blood cancers (1); breast adenocarcinoma (1); Burkitt lymphoma (1); cardiomyopathy (1); cholestasis (1); chronic kidney disease (1); chronic periodontitis (1); CNS lymphomas (1); ductal carcinoma in situ (1); endometrial cancer (1); esophageal cancer (1); Ewing sarcoma (1); Glucose intolerance (1); heart failure (1); hematological malignancies (1); Hypertension (1); Infertility (1); infiltrating ductal carcinoma (1).
A further 19 diseases each share a sentence with BTG2 in 1 paper.